NDC80 (NDC80 kinetochore complex component)
Diseases named in the same sentence as NDC80 in open-access papers (continued):
Sharing a sentence is not in itself a finding about the gene and the disease.
glioblastoma (4 papers, 2019 to 2024). The most malignant astrocytic tumor (WHO grade IV). "Human glioblastoma cells and normal cells were collected, and then RT-PCR, Western blot, and immunofluorescence were conducted to validate the expression of the NDC80 gene." (PMID 36238156, 2022). "NDC80 mRNA levels were determined by quantitative real-time reverse transcription-polymerase chain reaction (RT-PCR) between human glioblastoma cells and normal control cells." (PMID 36238156, 2022). "The RT-PCR, Western blot, and immunofluorescence results showed that the expression level of NDC80 was significantly higher in human glioblastoma cells than in normal cells." (PMID 36238156, 2022). "RT-PCR showed that NDC80 was upregulated significantly (p < 0.001) in human glioblastoma cells when compared with normal astrocytes (HA 1800)." (PMID 36238156, 2022). "Moreover, we identified that NDC80 increased the proliferation and invasion abilities of human glioblastoma cells." (PMID 36238156, 2022). "As shown in the scratch test results, knockdown of NDC80 protein reduced the migration ability of human glioblastoma cells (U251, U118, and A172) when compared with negative control cells." (PMID 36238156, 2022).
liver cancer (4 papers, 2018 to 2024). An epithelial or non-epithelial malignant neoplasm that arises from the liver. "Notably, mutations in NDC80 have been confirmed in the second most prevalent primary liver cancer (cholangiocarcinoma, CCA)." (PMID 37240068, 2023).
ovarian carcinoma (4 papers, 2021 to 2024). A malignant neoplasm originating from the surface ovarian epithelium. "BUB1B and NDC80 were validated at a transcription level in multiple cancer types based on the Oncomine database in that BUB1B (Median rank 132, p-value=1.54e-06) and NDC80 (Median rank 192.5, p-value=4.04e-08) were highly expressed in ovary cancer samples compared with normal ovary tissues." (PMID 33493131, 2021). "Our further qRT-PCR showed that seven hub genes (BUB1, KIF2C, NUP43, NDC80, NUF2, CCNB2 and CENPN) were differentially expressed in platinum-resistant ovarian cancer cells." (PMID 34820170, 2021). "Furthermore, in the CCLE database, the expression levels of BUB1B, NDC80, ELF3, TFAP2A and hsa-miR-655 were confirmed among different ovarian cancer cell lines." (PMID 33493131, 2021).
bladder cancer (3 papers, 2017 to 2024). "We performed protein-protein interaction analysis to select five important candidate genes (BUB1B, CCNB1, CDC25A, FBXO5, KIF20A, NDC80) regulated by PLK1 in bladder cancer cells using STRING software." (PMID 29246203, 2017). "To evaluate the significance of the five proteins in bladder cancer, we investigated the relationship between the expression of the five proteins (BUB1B, CCNB1, CDC25A, FBXO5, NDC80) and clinicopathological features." (PMID 29246203, 2017). "Four genes (BUB1B, CCNB1, CDC25A and NDC80) were expressed at higher levels in bladder cancer tissues than in normal bladder tissues, but the expression of FBXO5 was lower in bladder cancer than in normal tissues." (PMID 29246203, 2017).
cholangiocarcinoma (3 papers, 2021 to 2023). A carcinoma that arises from the intrahepatic biliary tree (intrahepatic cholangiocarcinoma) or from the junction, or adjacent to the junction, of the right and left hepatic ducts (hilar cholangiocarcinoma). "A cholangiocarcinoma patient was described with a fusion comprising FGFR2 and NDC80 (or HEC1, highly expressed in cancer 1)." (PMID 34207779, 2021).
COVID-19 (3 papers, 2021 to 2023). A disease caused by infection with severe acute respiratory syndrome coronavirus 2. "First, we compared the expression levels of five genes in COVID-19 and controls, finding that the expression of BIRC5, DTL, and NDC80 increased in COVID-19 while DNAJC4 and LILRB2 decreased." (PMID 37426635, 2023).
lung squamous cell carcinoma (3 papers, 2014 to 2023). "Finally, CDK1, PLK1, PCNA, ZWINT and NDC80 identified as hub genes for underlying molecular mechanisms of lung squamous cell carcinoma and lymphatic metastasis." (PMID 37185598, 2023). "Finally, CDK1, PLK1, PCNA, ZWINT and NDC80 identified as hub genes for underlying molecular mechanisms of lung squamous cell carcinoma lymphatic metastasis." (PMID 37185598, 2023). "NDC80 expression is significantly higher in squamous cell carcinoma of lung than adenocarcinoma in all three independent datasets." (PMID 24401611, 2014).
prostate carcinoma (3 papers, 2022 to 2024). A carcinoma that arises from epithelial cells of the prostate gland. "Furthermore, the turnover of NDC80 is indispensable for maintaining the conditions necessary for meiosis, in which the loss of phosphorylation of NDC80 at ser-55 and ser-69 causes an erroneous kinetochore-microtubule interaction in colon, lung, and prostate cancers." (PMID 36105209, 2022).
psoriasis (3 papers, 2005 to 2025). An autoimmune condition characterized by red, well-delineated plaques with silvery scales that are usually on the extensor surfaces and scalp. "NDC80, involved in mitotic spindle assembly, has been recognized as a biomarker in various autoimmune conditions, including psoriasis and type 1 diabetes." (PMID 40856249, 2025).
benign breast tumors (2 papers, 2011 to 2022). "Previous studies showed that NDC80, a vital member of the kinetochore assembly complex during mitosis, was upregulated in benign breast tumors and was related to the malignant features of BCa." (PMID 35568821, 2022). "Among the 14 benign breast tumors analyzed, 10 (71.4%) showed significant NDC80/HEC1 overexpression (> 3-fold higher than in normal breast tissues)." (PMID 21352579, 2011). "Alterations of nine of these genes, and particularly NDC80, were also detected in benign breast tumors, indicating that they may be involved in pre-neoplastic processes." (PMID 21352579, 2011).
malaria (2 papers, 2020 to 2021). Malaria is a serious and sometimes fatal disease caused by a parasite that commonly infects a certain type of mosquito which feeds on humans. "In summary, this study demonstrated the dynamic expression and location of NDC80 during the different proliferative stages of the malaria parasite and revealed both the disassembly and reassembly, as well as clustering, of kinetochores." (PMID 32501284, 2020). "Interestingly, the most abundant proteins co-purifying with the malaria parasite Ndc80 complex also have predicted RNA-binding functions." (PMID 33834005, 2021).
sarcoma (2 papers, 2021 to 2024). A usually aggressive malignant neoplasm of the soft tissue or bone. "We found that NDC80 complex components were significantly overexpressed in almost all TCGA cancer types, with the exception of mesothelioma (MESO), sarcoma (SARC), and uveal melanoma (UVM) due to limited availability of normal tissue data." (PMID 39513104, 2024).
squamous carcinoma (2 papers, 2014 to 2020). "Further, multivariate cox regression analysis showed that patients age, p-stage, M status and NDC80 expression work as independent prognostic indicators in adenocarcinoma, meanwhile, T stage, M status and MAD2L1 expression work as an independent indicators in squamous cell carcinoma." (PMID 32795325, 2020).
acute myeloid leukemia (1 paper, 2024). Acute myeloid leukemia (AML) is a group of neoplasms arising from precursor cells committed to the myeloid cell-line differentiation. "Specifically, the levels of NDC80 were only decreased in acute myeloid leukemia (LAML) and prostate adenocarcinoma (PRAD), and NUF2 downregulation was only observed in LAML and testicular germ cell tumors (TGCT)." (PMID 39513104, 2024).
aneuploidy (1 paper, 2023). Chromosomal disorder consisting of the presence a chromosomal abnormality in which there is an addition or loss of chromosomes within a set. "Overall, our results are consistent with initial pushing forces being important for accurate chromosome segregation, as their inhibition leads to severe oocyte aneuploidy when Ndc80-mediated pulling forces are also absent." (PMID 37419936, 2023).
Cirrhosis (1 paper, 2011). A chronic disorder of the liver in which liver tissue becomes scarred and is partially replaced by regenerative nodules and fibrotic tissue resulting in loss of liver function. "It is interesting to note that hub proteins are usually targeted, such as LCK, STAT1 and VCAN in Normal-Cirrhosis network, LCK in Cirrhosis-Dysplasia network, CDC2 and NDC80 in Dysplasia-Early HCC network and Early-Advanced network." (PMID 21824427, 2011).
colitis (1 paper, 2024). Inflammation of the colon. "A PPI network based on DEGs was constructed using STRING, and a highly interconnected cluster was identified as a potential functional molecular complex of colitis, including 8 hub genes, that is, NDC80, PBK, CEP55, RRM2, ASPM, NCAPG, TOP2A, and CDKN." (PMID 38661103, 2024).
head and neck cancer (1 paper, 2024). A primary or metastatic malignant neoplasm affecting the head and neck. "We used this database to assess the dependence of a large panel of head and neck cancer cell lines on the expression of PLK1, AURKA, TPR, NUF2, NDC80, and TTK." (PMID 39392349, 2024).
Hyperinsulinemia (1 paper, 2024). An increased concentration of insulin in the blood. "Additionally, hyperinsulinemia inhibited the transcriptome required for cell cohesion MELK, CDCA7, ESCO2, mitotic spindle assembly KIF15, SGO1, and AURKB, and kinetochore formation KNL and NDC80." (PMID 39768214, 2024).
malignant glioma (1 paper, 2022). A grade III or grade IV glioma arising from the central nervous system. "We discovered that NDC80, which has been shown to be important in other cancers, also has an important role in malignant gliomas." (PMID 36238156, 2022). "U251 and U-87MG cells displayed higher red fluorescence than HA1800 cells, suggesting that NDC80 expression in malignant glioma cells is higher than in normal cells." (PMID 36238156, 2022). "Then, we further examined the expression of NDC80 in different malignant glioma cells." (PMID 36238156, 2022). "In addition, we found that the translation level of NDC80 (p < 0.001) was also significantly increased in malignant glioma cells, as determined by Western blotting analysis." (PMID 36238156, 2022).
melanoma (1 paper, 2016). A malignant, usually aggressive tumor composed of atypical, neoplastic melanocytes. "NDC80, PLCE1 and AKAP13 have so far not been studied in melanoma." (PMID 27853253, 2016).
non-small cell lung adenocarcinoma (1 paper, 2023). Type of epithelial lung cancer arising from glandular origin. "In non-small cell lung adenocarcinoma cells, NDC80 activates cancer stem cell characteristics." (PMID 36635757, 2023).
serous adenocarcinoma (1 paper, 2012). An adenocarcinoma that is characterized by the presence of papillary patterns and cellular budding. "Furthermore, two independent gene expression studies show that NDC80, NUF2 and PTN were significantly aberrantly overexpressed in serous adenocarcinomas." (PMID 23056589, 2012).
vitiligo (1 paper, 2025). Generalized well circumscribed patches of leukoderma that are generally distributed over symmetric body locations and is due to autoimmune destruction of melanocytes. "We identified the elevated expression of HERC4 and NDC80 in vitiligo‐affected skin compared to healthy controls (p < 0.05) using the GEO dataset (GSE65127)." (PMID 40856249, 2025). "Taken together, these findings suggest that both HERC4 and NDC80, through their roles in immune modulation, oxidative stress, and cell survival, likely contribute to vitiligo pathogenesis by altering keratinocyte‐melanocyte interactions." (PMID 40856249, 2025). "We identified seven proteins (HEPHL1, PRDX1, DEFA1, CSGALNACT2, HERC4, NDC80, and SPHK2) causally associated with vitiligo risk." (PMID 40856249, 2025). "Notably, HERC4 and NDC80 exhibited robust expression in vitiligo lesions across validation datasets." (PMID 40856249, 2025). "Recent studies have shown that NDC80 regulates oxidative stress, modulates immune responses, and influences autophagy and ROS production, all of which may affect melanocyte survival in vitiligo." (PMID 40856249, 2025). "In addition, analysis of the GEO dataset (GSE65127) identified the significant upregulation of HERC4 and NDC80 in vitiligo lesions." (PMID 40856249, 2025). "Our integrative MR analysis identified novel protein biomarkers and promising therapeutic targets for vitiligo, particularly HERC4 and NDC80." (PMID 40856249, 2025).
cancer (80 papers, 2010 to 2026). A tumor composed of atypical neoplastic, often pleomorphic cells that invade other tissues. "NUF2, a protein within the NDC80 complex, has been identified as a cancer gene candidate because missense mutations, found across different tumor samples, cluster within NUF2’s calponin homology domain." (PMID 40161439, 2025). "SPC24, a component of the Ndc80 kinetochore complex, has been implicated in the development of various cancers." (PMID 38250721, 2024). "In conclusion, our study demonstrated that the NDC80 complex components were overexpressed in tumors compared with normal tissues, and high expression of the NDC80 complex components was associated with poor prognosis in pan-cancer." (PMID 39513104, 2024). "The results indicated that NDC80 complex components were positively associated with the cell cycle, proliferation, DNA damage, and DNA repair in the majority of cancer types except SPC24." (PMID 39513104, 2024). "Here, we have used CRISPR genomics to identify the Aurora A activator TPX2 and kinetochore protein NDC80 as key components explaining the cancer-associated PPP6C loss-of-function phenotype." (PMID 36897279, 2023). "Aberrant expression of the gene encoding the Ndc80 kinetochore complex component (NUF2) reportedly contributes to the progression of several human cancers." (PMID 35814368, 2022). "Furthermore, the expression levels of NDC80 complex components were positively associated with Th2 cell infiltration in the majority of cancer types." (PMID 39513104, 2024). "NDC80, which is a component of the essential kinetochore-associated NDC80 complex and is required for chromosome segregation and spindle checkpoint activity, was observed to inhibit cancer cell proliferation and induce apoptosis after knockdown." (PMID 34616422, 2021). "Although there are a large number of studies on the role of the NDC80 complex genes in cancer, this study has for the first time developed a risk assessment score by including clinical factors and expression of the NDC80 complex with diagnostic and prognostic value in LUAD." (PMID 32226507, 2020). "A new hypothesis: How does Ndc80 overproduction cause cancer?" (PMID 25557589, 2015). "CCNB1, PLK1, CDK1, BUB1B, AURKA, and NDC80 are genes involved in various stages of the cell cycle process, which is crucial from a cancer perspective." (PMID 40287845, 2025). "On the contrary, overexpression of NDC80 promotes cancer cell proliferation in vivo in a gastric cancer model." (PMID 39513104, 2024). "Taken together, these results provided strong evidence that the expression of NDC80 complex components influenced Th2 cell infiltration in pan-cancer." (PMID 39513104, 2024). "We found that similar with cell proliferation indicator - MKI67, the expression of NDC80 complex components was higher in tumor tissues than in normal tissues in the majority of cancer types." (PMID 39513104, 2024). "To investigate the prognostic value of NDC80 complex components in human cancers, we carried out the Kaplan-Meier analysis at the pan-cancer level." (PMID 39513104, 2024). "In this study, we explored the clinical significance of NDC80 complex components across TCGA cancer types." (PMID 39513104, 2024). "In accordance with previous studies, we found that the mRNA levels of NDC80 complex components were significantly upregulated in almost all TCGA cancer types suggesting an oncogenic role of NDC80 complex components in the majority of malignant tumors." (PMID 39513104, 2024). "We investigated the functional state of NDC80 complex components in various cancer types via the CancerSEA at the single-cell resolution." (PMID 39513104, 2024).